RN7SL105P (RNA, 7SL, cytoplasmic 105, pseudogene)
Gene: Miscellaneous RNA gene on chromosome 17 (1,604,374 to 1,604,672, reverse strand). Ensembl gene ENSG00000243704.
Homologues: Orthologues: chimpanzee Metazoa_SRP (96% identical), macaque Metazoa_SRP (88% identical). Paralogues in human: RN7SL2 (80% identical), RN7SL45P (80% identical), RN7SL1 (79% identical), RN7SL709P (79% identical), RN7SL7P (78% identical), RN7SL186P (78% identical), RN7SL732P (78% identical), RN7SL145P (78% identical), RN7SL30P (78% identical), RN7SL408P (78% identical), RN7SL726P (78% identical), RN7SL126P (77% identical), and 703 more.